IL6 (interleukin 6)
Diseases named in the same sentence as IL6 in open-access papers (continued):
Sharing a sentence is not in itself a finding about the gene and the disease.
ileitis (16 papers, 2011 to 2025). "Remarkably, Psae-challenge was accompanied by even more pronounced systemic secretion of pro-inflammatory cytokines such as TNF and IL-6 at day 9 post ileitis induction." (PMID 30761129, 2019). "We previously revealed that the activation of IL-6/Stat3 pathway via IL-6 trans-signaling plays a crucial role in the development of ileitis in SAMP1/Yit mice and murine CAC models." (PMID 27350830, 2016). "Previous studies conducted by the authors have also demonstrated that supplementation with acrylamide results in local ileitis with such symptoms as the increased synthesis of proinflammatory cytokines by gut-associated lymphoid tissue (GALT) (Interleukin 1β (IL-1β), IL-6, TNF-α)." (PMID 32225044, 2020). "Strikingly, even higher TNF and IL-6 levels could be measured in serum samples taken from Psae as compared to mock challenged hma mice with ileitis (p < 0.01)." (PMID 30761129, 2019). "Other factors that were only increased in the BALF of SHIP-1−/− mice with ileitis were IL-33 and TNFα, while IL-6, CCL2, and CCL4 were more significantly increased in the lungs of SHIP-1−/− mice with ileitis." (PMID 39432107, 2024). "In goats with TNBS-induced ileitis, TNBS enhanced the visceral motor response (VMR) and pain behavior response to CRD and increased the expression of IL-6, JAK-2, and STAT3 in the SCDH, periaqueductal gray (PAG), and rostral ventromedial medulla (RVM)." (PMID 34658755, 2021). "As for the ileum, subacute ileitis induction was further accompanied by elevated systemic concentrations of pro-inflammatory cytokines such as TNF and IL-6." (PMID 30967875, 2019). "In the present study, a chronic pain and VH, and marked expression of IL-6, pJAK2 and pSTAT3 in the PAG-RVM-SCDH axis were induced by ileitis, but attenuated by the repeated EA stimulations." (PMID 29209161, 2017). "Treatment of resveratrol suppresses cyclooxygenase-2 activity and modulates interferon-gamma (IFN-γ), TNF-α, IL-6 and MCP-1 expression in experimental ileitis." (PMID 22069489, 2011). "After acupuncture treatment in the 2,4,6-trinitrobenzene sulfonic acid (TNBS)-induced colitis or ileitis model, the level of TNF-α, IL-1β, and IL-6 and disease activity index, microscopic changes scour, and MPO level were decreased and caused to attenuate VH, and weight gain was improved." (PMID 34658755, 2021). "Polysaccharide–peptidoglycan complexes from L. casei Shirota significantly inhibited IL-6 production in LPS-stimulated colonic lamina propria mononuclear cells, RAW264.7 macrophages, and PBMCs from UC patients, leading to milder symptoms in ileitis mouse models." (PMID 41301527, 2025). "The inflammation in the ilea coincided with a significant increase in concentration of IL-6 protein in the serum, and while G-CSF levels were elevated, this was also observed in SHIP-1−/− mice without ileitis." (PMID 39432107, 2024).
kidney stones (16 papers, 2014 to 2026). "Clinical studies have linked nephrolithiasis with increased renal tubular damage and upregulation of inflammatory mediators like MCP-1 and interleukin-6." (PMID 40275250, 2025). "Substantial evidence indicates significant upregulation of IL-1β and IL-6 expression levels during nephrolithiasis development, particularly in calcium oxalate stone formation." (PMID 41019076, 2025). "It has been shown that CaOx crystals induce an inflammatory response through dendritic cell secretion of Il–1β, inflammasomes are involved in kidney stone pathogenesis and urine Il–6 levels are increased in patients with kidney stones." (PMID 26448465, 2015). "Given the importance of renal immune response in the pathophysiology of kidney stones, we investigated the correlations between miR-155 and important proinflammatory cytokines: IL-1β, IL-6, and TNF-α, a chemokine (RANTES) in the urine sediment." (PMID 25197634, 2014). "Natural active ingredients prevent and treat kidney stones by modulating inflammatory and oxidative stress related pathways, the mechanism of which involves inhibition of the release of pro-inflammatory factors such as IL-1β, IL-6, TNF-α etc." (PMID 41019076, 2025). "Repressing the release of pro-inflammatory cytokines, such as IL-1β, TNF-α, IL-6, and oxidative stress mediators, such as ROS, and MDA, can markedly relieve pain and cell apoptosis in kidney stones." (PMID 38154105, 2023). "In this study, Hyp intervention exhibited a notable decrease in the levels of IL-1β, IL-6, IL-8, and TNF-α in cell and rat models, suggesting the anti-inflammatory role of Hyp in nephrolithiasis." (PMID 36942317, 2023). "The aim of this study was to investigate the effects of SWL, for the treatment of kidney stones, on routine blood tests, and specific biomarkers, namely NGAL, IL-18, IL-6, IL-10 and IL-8." (PMID 32487191, 2020). "For clarifying the effects of Hyp on oxidative stress injury and inflammatory response in rats with renal calculi, we measured the levels of oxidative stress-related substances (MDA, LDH, ROS, and SOD) and inflammatory factors (IL-1β, IL-6, IL-8, and TNF-α) in the kidney tissue of rats." (PMID 36942317, 2023). "It has been previously demonstrated that IL-6 and MCP-1 indicated a close relationship between inflammation and kidney stones, while our previous research has confirmed that osteogenic transformation-related proteins BMP2 and OPN played important roles in stone formation." (PMID 35124708, 2022). "The role of IL6 in the inflammatory response during kidney stone formation is not clear." (PMID 37051106, 2023).
laryngeal carcinoma (16 papers, 2009 to 2025). Carcinoma that arises from the laryngeal epithelium. "According to the results of the present study, serum levels of IL-6 in patients were significantly associated with the severity of laryngeal cancer." (PMID 26082901, 2015). "Secondly, pro-inflammatory IL6 rs1800795 polymorphism was related to a higher risk of laryngeal cancer in a dominant model (p = 0.002, OR = 2.394 (1.376–4.163)), similar to the association found in CG+GG variants with increased oral cavity susceptibility (p = 0.018, OR = 2.265 (1.148–4.467))." (PMID 30959967, 2019). "We found that CTSL upregulates autophagy in laryngeal cancer cells by activating the IL6‐JAK‐STAT3 signalling pathway." (PMID 39893643, 2025). "We found that CTSL regulates the IL‐6‐JAK‐STAT3 signalling pathway to enhance autophagy in laryngeal cancer." (PMID 39893643, 2025). "Our previous studies found that CTSL promoted laryngeal cancer autophagy through the IL6‐JAK‐STAT3 signalling pathway." (PMID 41261048, 2025). "Following the manipulation of CTSL expression in normal laryngeal cells and laryngeal cancer cells, we monitored the expression of mRNA and proteins in the IL6‐JAK‐STAT3 pathway." (PMID 39893643, 2025). "Western Blot experiments showed a noticeable increase in the protein levels of the IL6‐JAK‐STAT3 pathway in laryngeal cancer tissues and cells." (PMID 39893643, 2025). "In summary, we found that CTSL promotes autophagy in laryngeal cancer through the IL6‐JAK‐STAT3 signalling pathway." (PMID 39893643, 2025). "In conclusion, our study suggests that CTSL promotes autophagy in laryngeal cancer by regulating the IL6‐JAK‐STAT3 signalling pathway." (PMID 39893643, 2025). "Knockdown of IL6 weakened the autophagy of CTSL‐overexpressing laryngeal cancer cells, while the addition of recombinant IL6 protein enhanced autophagy in CTSL‐overexpressing cells." (PMID 39893643, 2025). "Secretion of IL-6 has been suggested to act as a potential biomarker for assessing the aggressive tumor phenotype in laryngeal carcinoma." (PMID 28878571, 2017). "In this study, we identified and isolated ALDH+ and CD44+ CSC from laryngeal cancer cells as an approach to better predict the role of IL-6 in chemo-drug resistance." (PMID 28878571, 2017). "IL-6 knockdown can increase chemo-drug efficacy of cisplatin, inhibit tumor growth and reduce the potential for tumor recurrence and metastasis in laryngeal cancer." (PMID 28878571, 2017). "The results of our present study demonstrate distinct beneficial effects of IL-6 knockdown in combination with cisplatin treatment, and provide a theoretical base for applying siRNA techniques in the treatment of laryngeal cancer." (PMID 28878571, 2017). "Serum interleukin-6 (IL-6) levels are increased in laryngeal cancer patients as compared with healthy volunteers, and these serum levels show further increases as a function of malignancy progression." (PMID 28878571, 2017). "IL-6 levels in serum and cancer tissue are increased in laryngeal cancer patients as compared with healthy volunteers, suggesting that IL-6 can act as a potential biomarker for assessing tumor growth and malignancy progression." (PMID 28878571, 2017). "Accordingly, with the use of CSC, which is considered a very effective model for investigating drug-resistance, we demonstrate the importance of IL-6 signaling in triggering increased cisplatin efficacy in laryngeal cancer." (PMID 28878571, 2017). "The results of the present study primarily showed that the serum levels of IL-6 in patients with laryngeal cancer are significantly higher than in normal subjects in the control group." (PMID 26082901, 2015). "Given the non-normal distribution of IL-6 levels, the Mann-Whitney statistical test was used to determine that mean IL-6 levels in patients with laryngeal carcinoma were significantly higher than those in the control group (P= 0.0001)." (PMID 26082901, 2015).
laryngeal carcinoma (continued). "The present study aimed to investigate the relationship between serum levels of IL-6 and severity of laryngeal cancer." (PMID 26082901, 2015). "The activity of the IL6‐JAK‐STAT3 pathway was upregulated in laryngeal cancer tissues and cells." (PMID 39893643, 2025). "Furthermore, we elucidated that CTSL promotes laryngeal cancer progression through the IL6‐JAK‐STAT3 signalling pathway." (PMID 41261048, 2025). "To further investigate whether CTSL promotes autophagy in laryngeal cancer through the IL6‐JAK‐STAT3 signalling pathway, we knocked down IL6 in CTSL overexpression stable transfectants." (PMID 39893643, 2025). "Although we have elucidated the mechanism by which CTSL promotes autophagy in laryngeal cancer cells by activating the IL6‐JAK‐STAT3 signalling pathway at the molecular and genetic levels, increasing evidence suggests that cancer represents a complex pathological ecosystem." (PMID 39893643, 2025). "Moreover, hypoxia also induces alterations in the lipid metabolism of laryngeal carcinoma cells through the upregulation of the macrophage migration inhibitory factor (MIF)/IL-6/JAK-STAT pathway." (PMID 40724877, 2025). "Thus, the MIF/IL-6/JAK/STAT pathway is expected to provide a new approach for the treatment of laryngeal cancer." (PMID 36042480, 2022). "While IL-6/STAT3/HIF1 signaling has been reported to play an important role in the treatment of ovarian cell cancer, the issue of whether the IL-6/STAT3/HIF1 pathway may play a role in laryngeal cancer remains uncertain." (PMID 28878571, 2017). "Using in vitro cell lines and an in vivo xenograft model, we investigated whether knockdown of IL-6, as achieved using a siRNA technique, can increase the chemo-drug efficacy of cisplatin in laryngeal cancer." (PMID 28878571, 2017). "Taken together, our results suggest that IL-6 knockdown can increase chemo-drug efficacy, reduce drug resistance, inhibit tumor growth and reduce the potential for tumor recurrence and metastasis in laryngeal cancer." (PMID 28878571, 2017). "The IL-6/STAT3/HIF1 pathway may represent an important target for investigating therapeutic strategies for the treatment of laryngeal cancer." (PMID 28878571, 2017). "Elevated levels of IL-6 are also observed in tissue specimens of laryngeal cancer." (PMID 28878571, 2017). "Additionally, immunohistochemistry (IHC) confirmed that the levels of IL6 and LC3b in the CTSL‐knockdown group were significantly lower than those in the control group, further suggesting that CTSL promotes laryngeal cancer autophagy through the IL6‐JAK‐STAT3 signalling pathway." (PMID 39893643, 2025). "This study aimed to investigate whether interleukin-6 (IL-6) knockdown may enhance the efficacy of cisplatin in laryngeal cancer stem cells (CSC) and the potential involvement of the signal transducer and activator of transcription 3 (STAT3) and hypoxia-inducible factor 1 (HIF1) in this effect." (PMID 28878571, 2017). "Subsequently, we observed higher activity of the IL6‐JAK‐STAT3 pathway in TU212 and TU686 laryngeal cancer cells compared to normal laryngeal cells." (PMID 39893643, 2025). "Subsequently, we performed Opal Multiplex Immuno‐Histochemistry on tissue sections from laryngeal cancer patients and found a close relationship between CTSL and IL6, JAK and STAT3." (PMID 39893643, 2025). "The aim of this study was to assess the correlation between biomarkers of oxidative stress (MDA, SOD, and GPX) and inflammation (IL-1, IL-6, CRP) and postoperative pain management in surgically treated patients with laryngeal cancer." (PMID 37408225, 2023). "We assessed the serum levels of cytokines (IL–1, IL–2,IL–4, IL–6, IL–8, IL–10, IFN–gamma, TNF–alpha, GM–CSF), chemokines (MCP–1 and MIP–1alpha)and growth factors (VEGF and bFGF) in laryngeal cancer patients before, during and after surgery." (PMID 20108543, 2009). "In addition, the area of IL6‐positive cells and JAK‐high cells is also high in laryngeal cancer tissue." (PMID 39893643, 2025).
laryngeal carcinoma (continued). "Similarly, in laryngeal cancer cells TU212 and TU686, stable transfectants with high CTSL expression exhibited an increase in IL6‐JAK‐STAT3 pathway activity, while low expression stable transfectants showed a decrease." (PMID 39893643, 2025). "Interestingly, we found that CTSL promotes autophagy in laryngeal cancer through the IL6‐JAK‐STAT3 pathway, but IL6 does not affect CTSL expression." (PMID 39893643, 2025).
male infertility (16 papers, 2018 to 2025). The inability of the male to effect fertilization of an ovum after a specified period of unprotected intercourse. "In this research, we investigated the association between IL-6–174 G/C transversion and male infertility within a specific Iranian sub-population located in Kashan, Iran." (PMID 39968364, 2024). "As such, male infertility has also been linked to inflammatory biomarkers such as IL-6 and TNF-α and -β by disrupting the penile endothelium though increasing ROS testicular tissue levels." (PMID 38885232, 2024). "This disruption is caused by the secretion of inflammatory factors, such as IL-6, IL-1β, TNFα, and I IFNs, which disrupt sperm formation and transport, ultimately resulting in male infertility." (PMID 38300431, 2024). "A previous study conducted in the Uttar Pradesh population of North India also demonstrated an association between the IL-6–174 G/C transversion and male infertility." (PMID 39968364, 2024). "Despite the growing recognition of genetic factors in male infertility, the specific association between the IL-6–174 G/C genetic polymorphism and male infertility remains an area that needs further investigation." (PMID 39968364, 2024). "The objective of our study was to investigate the potential link between the IL-6–174G/C SNP and the risk of male infertility." (PMID 39968364, 2024). "This provides in vivo evidence to reinforce a causative role of IL-6 overexpression in male infertility." (PMID 31664153, 2019). "Our study suggests that the IL-6–174 G/C polymorphism may serve as potential protective factor against male infertility." (PMID 39968364, 2024). "Additionally, a significant association was observed in a dominant genetic model (GC + CC vs. GG) between the IL-6–174 G/C polymorphism and a decreased risk in male infertility, extending to the subgroups of oligozoospermia and asthenospermia." (PMID 39968364, 2024). "Our results uncover a previously unknown physiological role of NCOA5 in the regulation of epididymal sperm maturation and suggest that NCOA5 deficiency could cause male infertility through increased IL-6 expression in epididymis." (PMID 31664153, 2019). "Therefore, this may explain the protective role of the IL-6–174 G/C polymorphism against male infertility." (PMID 39968364, 2024). "Elevated IL-6 levels are commonly observed in male infertility and induce testicular oxidative stress." (PMID 40756901, 2025). "This investigation explores the correlation between the IL-6–174 G/C transversion and male infertility." (PMID 39968364, 2024). "Our findings suggest that the IL-6–174 G/C transversion could potentially serve as a protective genetic factor against male infertility." (PMID 39968364, 2024). "The results highlight IFN-γ, IL-1β, IL-6, LPO, 8-OHdG, and TAC evaluation in seminal plasma for a comprehensive state of male infertility to improve therapeutic intervention in male partners of infertile couples and to prevent infections or diseases." (PMID 34577786, 2021). "Moreover, active compounds from natural products in classical prescriptions have been shown to improve male infertility by modulating SASP markers, including IL-1β, IL-6, and TNF-α." (PMID 40552151, 2025). "Gossypol-induced male infertility markedly and significantly increased the levels of testicular TBARS, NO, TNF-α, ADAM-17, and interleukins (IL-1β, IL-6, and IL-18) while significantly decreasing the levels of both TIMP-3 and IL-12 compared with those of the control group." (PMID 29849861, 2018).